MCMBP (minichromosome maintenance complex binding protein)
Description:
Associated component of the MCM complex that acts as a regulator of DNA replication. Binds to the MCM complex during late S phase and promotes the disassembly of the MCM complex from chromatin, thereby acting as a key regulator of pre-replication complex (pre-RC) unloading from replicated DNA. Can dissociate the MCM complex without addition of ATP; probably acts by destabilizing interactions of each individual subunits of the MCM complex. Required for sister chromatid cohesion.
Synonyms: MCM-BP; C10orf119; FLJ13081
Tractability: PROTAC: ubiquitination databases record sites on it; its protein half-life has been measured.
Gene: Protein-coding gene on chromosome 10 (119,829,060 to 119,892,556, reverse strand). Ensembl gene ENSG00000197771.
Subcellular location: Nucleus
Subcellular location (Human Protein Atlas): Nucleoplasm; Cell Junctions; Cytosol
Gene Ontology:
Molecular function: chromatin binding; protein binding
Biological process: DNA-templated DNA replication; sister chromatid cohesion
Cellular component: MCM complex; nucleoplasm; nucleus
Genetic constraint (gnomAD): Loss-of-function variants: 23 observed, 60.67 expected, observed/expected ratio (o/e) 0.38, 90% interval 0.27 to 0.54. The upper end of that interval is the gene's LOEUF score, 0.54, which puts it in group 2 of 6, group 1 being the genes least tolerant of losing a copy. Missense variants: 507 observed, 631.01 expected, observed/expected ratio (o/e) 0.8, 90% interval 0.75 to 0.87. Synonymous variants: 211 observed, 228.43 expected, observed/expected ratio (o/e) 0.92, 90% interval 0.82 to 1.03.
Homologues: Orthologues: chimpanzee MCMBP (100% identical), macaque MCMBP (99% identical), dog MCMBP (97% identical), pig MCMBP (97% identical), guinea pig MCMBP (97% identical), rabbit MCMBP (95% identical), mouse Mcmbp (93% identical), rat Mcmbp (91% identical), tropical clawed frog mcmbp (68% identical), zebrafish mcmbp (65% identical), Drosophila melanogaster CG3430 (34% identical).
Diseases named in the same sentence as MCMBP in open-access papers:
MCMBP is named in the same sentence as 5 diseases in open-access papers, as found by Europe PMC text mining. Sharing a sentence is not in itself a finding about the gene and the disease. The quoted sentences say what the papers report.
colorectal cancer (1 paper, 2025). A primary or metastatic malignant neoplasm that affects the colon or rectum. "Similarly, in colorectal cancer, elevated MCMBP expression is linked to increased recurrence risk, suggesting its utility as a diagnostic biomarker." (PMID 41346611, 2025).
pancreatic ductal adenocarcinoma (1 paper, 2025). An infiltrating adenocarcinoma that arises from the epithelial cells of the pancreas. "Microchromosome maintenance protein-binding protein (MCMBP) is aberrantly expressed in cancers and proposed as a diagnostic marker and therapeutic target, but its role in pancreatic ductal adenocarcinoma (PAAD) remains unclear." (PMID 41346611, 2025).
cancer (3 papers, 2020 to 2025). A tumor composed of atypical neoplastic, often pleomorphic cells that invade other tissues. "Collectively, these results suggest that aberrant MCMBP expression is closely associated with cancer progression." (PMID 41346611, 2025). "Pan-cancer analysis revealed that MCMBP overexpression correlates with poor prognosis, including in PAAD." (PMID 41346611, 2025). "To explore the prognostic significance of MCMBP expression, we performed univariate Cox regression analysis across 33 cancer types to assess its correlation with overall survival (OS)." (PMID 41346611, 2025). "Pan-cancer analysis using data from TCGA and GTEx revealed widespread dysregulation of MCMBP expression in multiple cancer types." (PMID 41346611, 2025). "KEGG analysis further indicated enrichment of the “PD-L1 expression and PD-1 checkpoint pathway in cancer” under high MCMBP protein levels, suggesting that MCMBP may promote immune evasion by regulating PD-L1 and correlate with poor prognosis." (PMID 41346611, 2025). "A recent article showed that MCMBP accumulates at high levels in cancer cells, which may be related to the overexpression of MCM2–7 observed in many cancerous tissues." (PMID 35438632, 2022). "Interestingly, our current proteomics data now place MYSM1 in a functional network with PCNA, RFC, HELLS, and MCMBP with potential relevance in hematopoiesis and in cancer progression." (PMID 32466590, 2020).
tumor (1 paper, 2025). "Univariate Cox regression analysis revealed that, in the TCGA cohort, MCMBP expression, T stage, N stage, and tumor grade were all significantly associated with PAAD prognosis." (PMID 41346611, 2025). "Analysis of the top 200 genes most correlated with MCMBP protein abundance in the TCGA-CPTAC database revealed, by GO enrichment, that these genes were primarily associated with tumor cell proliferation, migration, and immune responses upon MCMBP upregulation." (PMID 41346611, 2025). "Ge-ne function and immune infiltration analyses indicated that high MCMBP expression is closely associated with immune-related pathways, tumor cell proliferation, survival, and immune cell differentiation, and may promote Treg accumulation and immune ch-eckpoint upregulation." (PMID 41346611, 2025). "As a biomarker related to immunotherapy, MCMBP possesses the potential to promote tumor growth and synergize with immune therapies." (PMID 41346611, 2025). "MCMBP expression was elevated in tumor tissues compared to normal controls in both the GSE62452 and GSE183795 cohorts." (PMID 41346611, 2025). "Based on analyses using the DiseaseMeth and TCGA databases, we found that MCMBP methylation levels are significantly higher in normal tissues than in tumor tissues." (PMID 41346611, 2025). "To facilitate clinical translation, we integrated the independent prognostic factors—age, tumor grade, tumor stage, and MCMBP expression—into a nomogram for predicting OS in both TCGA and CPTAC cohorts." (PMID 41346611, 2025). "Enrichment of specific protein domain binding also implies a role for MCMBP-mediated epigenetic regulation in tumor progression." (PMID 41346611, 2025). "Multivariate analysis further confirmed that MCMBP expression and tumor grade were independent prognostic factors in the TCGA cohort." (PMID 41346611, 2025). "Colony formation assays revealed that MCMBP knockdown significantly suppressed proliferation in both cell lines, suggesting a potential role for MCMBP in promoting tumor cell growth." (PMID 41346611, 2025). "In hepatocellular carcinoma, MCMBP promotes tumor progression by regulating DNA replication and the cell cycle." (PMID 41346611, 2025). "ESTIMATE analysis showed that high MCMBP expression was associated with higher ESTIMATE, Immune, and Stromal scores, and lower Tumor Purity, suggesting its potential involvement in modulating the TME." (PMID 41346611, 2025). "Similarly, in the CPTAC cohort, MCMBP expression levels were significantly elevated with advancing tumor stage." (PMID 41346611, 2025). "This indicates that MCMBP fosters an immunosuppressive microenvironment not only by upregulating PD-L1 on tumor cells but also by directly impairing T cell activation, thereby providing a more comprehensive preliminary exploration mechanistic basis for its role in immune evasion." (PMID 41346611, 2025). "GO enrichment analysis showed that MCMBP may enhance tumor-stroma interactions through the regulation of extracellular matrix structural constituents and focal adhesion pathways." (PMID 41346611, 2025). "In the CPTAC cohort, MCMBP expression and tumor stage were significantly correlated with prognosis." (PMID 41346611, 2025). "In the TCGA cohort, MCMBP expression increased significantly with higher tumor grade." (PMID 41346611, 2025). "Furthermore, our functional co-culture assays demonstrated that MCMBP-overexpressing tumor cells directly suppressed T-cell effector function, as evidenced by diminished IFN-γ secretion and reduced STAT5 phosphorylation in T cells." (PMID 41346611, 2025). "Previous KEGG/GO analyses indicated a potential role for MCMBP in tumor immunity." (PMID 41346611, 2025). "Dysregulation of MCMBP may contribute to chromosomal instability (CIN), a recognized hallmark of tumor progression." (PMID 41346611, 2025).
tumor (continued). "The concordance between the pathways targeted by these effective MCMBP-inhibiting compounds and previously identified MCMBP-associated functions collectively suggests that the tumor-promoting role of MCMBP in PAAD is likely mediated through the regulation of these specific signaling pathways." (PMID 41346611, 2025). "Furthermore, MCMBP appears to promote cell proliferation and survival via receptor binding, protein binding, and growth factor binding signaling pathways, suggesting a potential role in facilitating tumor cell migration and invasion." (PMID 41346611, 2025). "Similarly, MCMBP expression and tumor stage were independent predictors in the CPTAC cohort." (PMID 41346611, 2025). "Furthermore, high MCMBP expression correlates with elevated levels of m6A “readers” (IGF2BP1, IGF2BP3) and “writers” (VIRMA, YTHDF3), a state thought to promote tumor progression by enhancing the stability and translation of oncogenic mRNAs." (PMID 41346611, 2025). "To investigate MCMBP expression in PAAD, we performed immunohistochemical (IHC) staining and scoring on tissue samples from 117 PAAD patients, including 47 paired tumor and adjacent non-tumor samples and 23 unpaired tumor samples (Figures 9A2, B2)." (PMID 41346611, 2025).
MCMBP also shares sentences with these, for which no sentence is quoted: pancreatic adenocarcinoma (1 paper).